NR3C1 (nuclear receptor subfamily 3 group C member 1)
Diseases named in the same sentence as NR3C1 in open-access papers (continued):
Sharing a sentence is not in itself a finding about the gene and the disease.
depression (continued). "Similarly, maternal smoking and depression during pregnancy have been associated with altered methylation of placental stress-regulatory genes, including NR3C1 and HSD11B2, the latter encoding an enzyme that inactivates cortisol." (PMID 41179817, 2025). "The interaction between a third site, (cg25708981 within NR3C1) and measures of depression symptoms (HADS-D in AIBL and GDS in ADNI) was associated with multiple regional longitudinal brain volumes across both cohorts and survived FDR correction, highlighting its significance." (PMID 40964007, 2025). "From a new perspective, the study explores the molecular interactions between stress-induced damage and cholesterol metabolism, elucidating the roles of NR3C1/NRIP1/NR1H2 in the mechanisms underlying depression-like behavior induced by short-term restraint stress." (PMID 39125645, 2024). "DNA methylation levels in the promoter region of NR3C1 were associated with childhood maltreatment (CM) and depression, suggesting that CM exposure may biologically embed these critical HPA axis genes." (PMID 38249586, 2023). "Homozygous mutations in NR3C1 rs41423247 are associated with depression." (PMID 37140907, 2023). "Available studies show that hypermethylation of the NR3C1 gene and decreased peripheral NR3C1 mRNA expression could be considered markers of increased susceptibility to early-onset depression." (PMID 34590201, 2023). "In human studies, increased methylation of 11β-HSD2 and Nr3c1, a gene encoding for glucocorticoid receptor (GR), in the placentas from mothers who reported anxiety and depression during pregnancy was positively correlated with impairments in infant neurobehavior." (PMID 37110193, 2023). "Importantly, NR3C1 methylation shows a sex-dependent association between maternal depression and symptoms of anxiety and depression in children." (PMID 34276306, 2021). "Based on these findings, it can be postulated that NR3C1 methylation status may be associated with cardiac prognosis of ACS independently of or interactively with depression." (PMID 32218512, 2020). "This study aimed to investigate whether NR3C1 methylation status was associated with the long-term prognosis of acute coronary syndrome (ACS) considering depression and cardiovascular status at the early phase of ACS." (PMID 32218512, 2020). "Similarly, associations of depression with worse long-term cardiac outcomes were stronger in ACS patients with higher NR3C1 methylation status." (PMID 32218512, 2020). "For example, the NR3C1 gene encodes the glucocorticoid receptor (GR) and the single nucleotide polymorphism (SNP) BclI rs41423247 has been associated with an increased risk of major depressive disorder." (PMID 32957930, 2020). "Moreover, another monozygotic twin study revealed that DNAm at the NR3C1 mediated the association between childhood trauma and depression." (PMID 33117794, 2020). "Hypermethylation or hypomethylation of key genes for the development of depression in men, such as the AR, BDNF, 5HTT, FKBP5, and NR3C1 constitute independent risk and resilience factors for depression, AUDs, and suicidal behavior and further interact with the prior described genetic predisposition." (PMID 28096796, 2016). "FK506 binding protein 5 and NR3C1 were shown to be associated with depression and suicide attempts." (PMID 28096796, 2016). "The results suggest that higher methylation in NR3C1 in relation to early life adversities may also have causative roles for depression, which is closely related to suicide." (PMID 24465557, 2014). "The main aim of the present study has been to examine, whether genetic variants of NR3C1 gene are associated with depression, especially with rDD in population of central Poland." (PMID 23073785, 2013). "Accordingly, NR3C1 variants have been associated with hippocampal volume and unipolar depression." (PMID 23805179, 2013).
depression (continued). "NR3C1 methylation at CpG site 1, CpG site 4, as well as average methylation percentage, were negatively associated with resilience level after controlling for covariates such as maternal age, pregnancy complications, parity, history of depression, and pre-pregnancy BMI." (PMID 39257475, 2024). "Recent reviews on NR3C1 DNA methylation highlighted the complexity of the associations pertaining to this epigenetic system in relation to depression, suggesting a potential inverted U-shaped relationship similar to that described for peripheral cortisol and depression." (PMID 39257475, 2024). "For example, DNA methylation might be a potential link between environmental factors and the occurrence of depression; a review showed that BDNF and NR3C1 gene methylation levels were associated with depression, but the relationship between SLC6A4 and depression was found to be contradictory." (PMID 37181891, 2023). "Although previous studies suggested that hypermethylation of NR3C1 methylation was associated with lower GR mRNA as well as abnormal cortisol response, further investigations for underlying biological mechanisms between NR3C1 methylation and cardiac outcomes with interaction of depression." (PMID 32218512, 2020). "Methylation of the glucocorticoid receptor gene NR3C1 through epigenetic processes, crucial in the hypothalamic-pituitary-adrenal axis modulation, our primary stress response system, has been linked to psychopathological conditions such as anxiety and depression." (PMID 28427329, 2017). "The association between NR3C1 haplotypes with depression and anxiety may therefore be complex." (PMID 25009637, 2014). "Prenatal depression was positively correlated with the degree of methylation in maternal blood, and depression predicted methylation in the NR3C1 promoter region in Chinese women during the COVID-19 lockdown." (PMID 41440377, 2025). "Based on the concept that NR3C1 is critical for glucocorticoid signaling and stress regulation, hypermethylation of NR3C1 in individuals exposed to childhood adversity correlates with increased vulnerability to PTSD, depression, and suicide risk." (PMID 41234420, 2025). "In this study, we found that the levels of BDNF and Nr3c1 genes in the brain decreased following exposure to restraint stress and the onset of anxiety and depression symptoms." (PMID 40806449, 2025). "For example, in one study, newborns of mothers who experienced depression during pregnancy showed increased NR3C1 methylation, which correlated with heightened cortisol stress responses in the infants." (PMID 40243774, 2025). "Specifically, most studies reported increased methylation at BDNF, SLC6A4, and NR3C1, while FKBP5 typically showed decreased methylation associated with depression." (PMID 41179817, 2025). "Interestingly, a meta-analysis of DNA methylation in the BDNF and NR3C1 genes in the context of depression showed that BDNF hypermethylation may be associated with the risk of MDD in Asian populations, whereas NR3C1 hypermethylation was linked to depressive symptoms but not to MDD itself." (PMID 41303216, 2025). "A Mann–Whitney U test indicated that women with lower personality vulnerability to depression had higher NR3C1 methylation at CpG site 2 as compared to those with higher personality vulnerability (p < 0.01)." (PMID 39257475, 2024). "This study predicted that linalool, p-cymene, α-terpinene, terpinen-4-ol, and α-terpineol primarily contribute to CBEO’s anti-depressant effect, mainly via interactions with OPRM1, PTGS2, ESR1, SLC6A4, DRD2, and NR3C1, the six depression-related targets." (PMID 38567354, 2024). "We now report the novel implication of the NR3C1 gene in the risk of PCOS, which is also a complex disorder carrying increased risks for T2D and depression." (PMID 38217051, 2024).
depression (continued). "The study aims to investigate the relationship between peritraumatic distress, prenatal perceived stress, depression, and glucocorticoid receptor (NR3C1) DNA methylation among pregnant women who experienced COVID-19 lockdown in China." (PMID 36091061, 2022). "miR-382-5p targeted NR3C1 and inhibited the expression of NR3C1 in rats’ hippocampi, leading to more severe and higher prevalence of depression with an elevated latency to feed and immobility time." (PMID 35884935, 2022). "Further, our study demonstrated a correlation between prenatal depression exposure and DNA methylation at a specific CpG 8 site of NR3C1 gene." (PMID 36091061, 2022). "The NR3C1 gene and the region of exon 1F have been extensively studied regarding disturbed emotional states (depression and anxiety) during pregnancy and associated with DNA methylation changes (higher methylation levels) of placental NR3C1 exon 1F." (PMID 36430406, 2022). "In particular, it has been shown that NR3C1 methylation contributes significantly to our understanding of both depression and dysregulation of the HPA axis." (PMID 36583185, 2022). "Effects of peritraumatic distress, perceived stress and depression on NR3C1 gene CpG sites methylation among pregnant women." (PMID 36091061, 2022). "Levels of NR3C1 methylation among pregnant women, overall and by demographic groups, and levels of depression." (PMID 36091061, 2022). "Candidate genes that undergo DNA methylation, such as brain-derived neurotrophic factor (BDNF), NR3C1 (encoding the glucocorticoid receptor), SLC6A4 (encoding the serotonin transporter), have been regarded as potential biomarkers of depression." (PMID 33815064, 2021). "It is among the first to consider the joint contribution of prenatal exposure to depression and Pb in relation to fetal growth and to gestational DNA methylation to NR3C1 DNA methylation." (PMID 34831923, 2021). "Lead (Pb) and depression independently influence birth outcomes and offspring NR3C1 (glucocorticoid receptor) DNA methylation." (PMID 34831923, 2021). "In patients with post-stroke depression (PTSD), NR3C1 methylation was associated with treatment outcome." (PMID 33804455, 2021). "The results showed that alcohol consumption, overweight, and high cortisol levels were related to NR3C1 demethylation, while depression was related to its methylation." (PMID 33762648, 2021). "Molecular docking showed that telocinobufagin and beta-sitosterol, the active ingredients of Shan-Zhu-Yu, can act on NR3C1, Bax, and Bcl-2 to treat depression." (PMID 33299459, 2020). "In the depression animal model established by maternal deprivation and social isolation, Dnmt1 expression and Nr3c1 promoter methylation level of female rats were higher than those in male rats." (PMID 33101076, 2020). "One important limitation of the present study is that only one CpG island in the NR3C1 gene was examined, although this area has been repeatedly investigated in previous epigenetic studies pertaining to both depression and adverse life events." (PMID 32218512, 2020). "Studies over the past years suggest that the methylations of some specific genes such as BDNF, SLC6A4, and NR3C1 play an important role in the development of depression." (PMID 33101076, 2020). "Hence, HPA-axis sensitivity and stress responsivity may be permanently altered by prenatal depression through increased fetal NR3C1 methylation and lower GR density, which eventually may lead to a heightened susceptibility for psychopathology such as depression and anxiety." (PMID 32116849, 2020). "Certain studies showed high methylation level of glucocorticoid receptor gene, NR3C1, in cord blood from the newborns whose mothers experienced depression or anxious mood during pregnancy." (PMID 32156057, 2020).
depression (continued). "Synergistic effects of depressive disorder and NR3C1 hypermethylation on long-term cardiac outcomes in ACS were found." (PMID 32218512, 2020). "DNA methylation of NR3C1 and NR3C2 were measured in placental and infant buccal samples, and it is found that maternal early pregnancy depressive disorder and symptoms were associated with lower DNA methylation at NR3C2 CpG_24 in placental tissue." (PMID 33015076, 2020). "NR3C1 methylation status represents a candidate prognostic biomarker for ACS in combination with a diagnosis of depressive disorder." (PMID 32218512, 2020). "NR3C1 hypermethylation predicted worse long-term prognosis of ACS only in the presence of depressive disorder with significant synergistic interaction terms and independent of potential confounding factors." (PMID 32218512, 2020). "Baseline evaluations were made from 2007 to 2012, including DSM-IV depressive disorder, NR3C1 methylation, and various demographic and clinical characteristics such as cardiovascular risk markers." (PMID 32218512, 2020). "The NR3C1 methylation x depressive disorder multiplicative interaction terms were statistically significant for the composite MACE, all-cause mortality, and cardiac death outcomes." (PMID 32218512, 2020). "Previous studies indicated that low levels of NR3C1 mRNA were observed in individuals with co-occurring child abuse and suicide, schizophrenia, and depression." (PMID 31689998, 2019). "Among those studies, changes in DNA methylation of the Nr3c1 gene were the first to be linked to altered gene expression, HPA dysfunction, and anxiety-and depression-related phenotypes induced by early-life adversity in rats and humans." (PMID 31031589, 2019). "These predictions were tested in a longitudinal study, using measures of prenatal and postnatal depression, of NR3C1 1-F promoter region methylation at 14 months of age, and anxious depressed symptoms in children across the preschool period." (PMID 31438539, 2019). "It has recently been found that NR3C1 methylation is positively correlated with hippocampal volume in patients with depression." (PMID 29415058, 2018). "For NR3C1 promoter methylation, depression, hostility, happiness and life satisfaction, all exhibited positive and non-significant associations." (PMID 26733571, 2016). "The consequences of pre- and post-natal depression on the methylation status of the NR3C1 and HSD11B2 genes have also been assessed in the placenta." (PMID 27918480, 2016). "Enhanced methylation of the exon NR3C1 1F promoter has been also found in the peripheral blood of persons with major depressive disorder and borderline personality disorder as a result of childhood maltreatment." (PMID 26366233, 2015). "Increased methylation of NR3C1 and BDNF genes is associated with increased risk of depression, suggesting that DNA methylation may play a role in the pathophysiology of the disorder." (PMID 41373485, 2025). "Similarly to NR3C1, the co-occurrence of other psychiatric disorders (e.g., depression, PTSD, eating disorders) is especially important in the case of BDNF methylation changes." (PMID 41303216, 2025). "Finally, both NR3C1 and HSPBP1 genes were selected because they were differentially expressed in the brains of individuals with mental disorders, with NR3C1 also being differentially expressed in the blood of BHRCS individuals with major depressive disorder." (PMID 40018685, 2025). "However, a prior study of PBMC NR3C1 methylation found that depression moderated methylation effects on acute coronary syndrome outcomes, supporting the role of depression moderating the impact of methylation on disease." (PMID 40964007, 2025). "Epigenetic changes have been well-established in BDNF, COMT, FKBP5, NR3C1, SLC6A4, and DRD2, genes associated with psychiatric disorders, including schizophrenia, major depressive disorder (MDD), bipolar disorder (BP), post-traumatic stress disorder (PTSD), and autism spectrum disorder (ASD)." (PMID 41234420, 2025).
depression (continued). "Furthermore, we detected an interaction effect between current distress level due to interpersonal traumatic events in childhood and NR3C1 CpG sites 3 and 4, in relation to personality vulnerability to depression." (PMID 39257475, 2024). "Changes in NR3C1 gene methylation in the segment analyzed have previously been found to be related to certain psychiatric disorders, such as depression and post-traumatic stress, eating disorders, abuse, and trauma or adverse events in childhood or during the prenatal period." (PMID 38633601, 2024). "However, correlations have been found between the methylation of two CpG loci located in the NR3C1 gene promoter and the specific symptoms of depression." (PMID 38792892, 2024). "Moreover, the interaction term between current distress level due to total traumatic event and each NR3C1 CpG site in relation to personality vulnerability to depression was significant on CpG 2 (B = 0.07, CI95% 0.01–0.13)." (PMID 39257475, 2024). "These factors were linked to non-methylation of NR3C1, while depression was associated with methylation, resulting in unique clinical implications." (PMID 38633601, 2024). "Finally, all of the parameters associated with adherence to an industrialized (ultra-processed) diet resulted in epigenetic changes in NR3C1, a gene related to chronic stress, stress responsiveness, and depression." (PMID 38633601, 2024). "Specifically, we investigated the genetic and epigenetic correlates of key stress-associated genes (NR3C1, NR3C2, FKBP5, GILZ, SLC6A4) with psychological characteristics (depression, anxiety, and stress) often included in DD diagnostic criteria, as well as with brain EEG findings." (PMID 38391714, 2024). "Therefore, it is reasonable to believe that NR3C1 methylation regulation is a potential biological marker of AUD-induced depression." (PMID 37373281, 2023). "Methylation analyses of 9 promoter/regulatory regions of genes known to be implicated in depression/PTSD (ADCYAP1, BDNF, CRHR1, DRD2, IGF2, LSD1/KDM1A, NR3C1, OXTR, SLC6A4) were performed on DNA from blood samples by the MassARRAY EpiTYPER platform, with MassCleave settings." (PMID 36001138, 2023). "In the present study, we aimed to investigate whether and to what extent prenatal peritraumatic distress, perceived stress, and depression in Chinese pregnant women during COVID-19 lockdown affect maternal NR3C1 DNA methylation." (PMID 36091061, 2022). "Similarly, hypermethylation on NR3C1 promoter in downregulated gene expression was determined to be more likely in suicidal patients with a major depressive disorder compared to in the control subjects." (PMID 35456368, 2022). "Epigenetic changes of the NR3C1 gene affect coping style and depression vulnerability." (PMID 36233250, 2022). "Prenatal depression was positively correlated with the degree of methylation in venous blood from the mother (r = 0.59, p = 0.001), and depression predicted methylation of NR3C1 gene at the CpG 8 site (β = 0.05, p = 0.03)." (PMID 36091061, 2022). "This hypothesis is supported by the concept that dysregulation of NR3C1 leads to depression and suicide by disturbing the function of the hypo-thalamic-pituitary-adrenal axis." (PMID 34177643, 2021). "We found some evidence to suggest NR3C1 methylation may be likewise influenced by both gestational Pb and depression exposures, which in turn may influence infant outcomes." (PMID 34831923, 2021). "We hypothesized that gestational Pb and depression would jointly influence birth outcomes and NR3C1 methylation." (PMID 34831923, 2021). "Marginally significant interactions between Pb and depression were observed for NR3C1 factors 1 and 2, indicating that higher levels of both exposures may be jointly influencing methylation extents at the CpGs loading on these factors." (PMID 34831923, 2021).